CD68 (CD68 molecule)
Diseases named in the same sentence as CD68 in open-access papers (continued):
Sharing a sentence is not in itself a finding about the gene and the disease.
tumor (continued). "CD68+ M1 macrophages, known for its tumor-inhibiting ability, are the major TNF-α-producing immune cells in the tumor microenvironment." (PMID 38037106, 2023). "We analyzed the correlation by performing immunohistochemical staining for CD68 in serial tumor tissue slices from the SYSUCC cohort patients." (PMID 37865750, 2023). "We then found that the patients of T3–T4 showed higher CD68+, CD68+PD‐L1−, and CD68+PD‐L1+ TAMs infiltration than those of T2, indicating the correlation between TAMs and tumor invasion." (PMID 36043478, 2023). "CD146 was expressed on a subset of CD68+ macrophages in the tumor margins between tumor tissue and tumor-adjacent tissue, which was confirmed by FCM." (PMID 37308559, 2023). "In both syngeneic mouse tumor models, the infiltration of CD68+ macrophages was increased by copanlisib alone and in combination with anti-PD-1." (PMID 37935952, 2023). "Tumor-associated macrophages (TAMs) (CD68+ cells) are highly present in several cancer types, including CCA, where they infiltrate the tumor bed and its margins and correlate with poor prognosis." (PMID 36980187, 2023). "In most tumor tissue, we observed high level CD68+ and MCR1+ macrophage infiltration, and both of these are associated with an unfavorable prognosis of HCC." (PMID 36902024, 2023). "PD-L1 is expressed mainly by aggressive primary tumor cells and by CD68/CD163-positive M2 macrophages in patients with colorectal cancer with high microsatellite instability." (PMID 37525217, 2023). "The marginal region was divided into twelve areas from 300 μm inside to 300 μm outside the tumor margin, and the density of CD68+ cells was examined in each area." (PMID 37792212, 2023). "The mean values of CD68+ macrophages in the tumor center and invasion front were 14.01 and 44.85, respectively." (PMID 36836239, 2023). "Of 282 cases, 93 (33%) showed high CD47 tumor cell expression, and high counts of CD68 TAMs were found in 68 cases (24%)." (PMID 36598153, 2023). "In conclusion, we report that high numbers of CD68- and PD-L1-expressing cells within tumor tissue prior to MKI treatment can be a biomarker used to predict PFS in patients with HCC." (PMID 37189554, 2023). "The CD3-positive cells were more abundant in the high-LMR tumor than in the low-LMR tumor, whereas the CD68-positive cells were less abundant in the high-LMR tumor than in the low-LMR tumor." (PMID 37400504, 2023). "The other cell type markers CD107a+ CD8+ and CD68+CD107a- were similarly distributed in tumor and stroma (p=0.27 and p=0.50)." (PMID 37007114, 2023). "Tumor tissues with higher EGFR VAF were associated with lower cell infiltration such as CD3+ T cells, CD20+ B cells, CD56+ natural killer cells, CD68+ macrophages, CD8+ T cells, and only CD3+ T cells showed a lower spatial distribution heterogeneity." (PMID 37035883, 2023). "To assess the infiltration of TREM2+ TAMs in tumor tissues, we labeled macrophages with CD68 and subsequently observed the expression of TREM2 on this cell type." (PMID 37187751, 2023). "xCT expression in tumor tissues, especially in CD68+ macrophages, can serve as a reliable factor to predict the prognosis of HCC patients." (PMID 36442849, 2023). "Similar to the expression pattern of PD-L1, CD68+ macrophages were found evenly distributed inside tumoral lesions and at the invasion fronts in both, the primary tumor and liver metastases." (PMID 37449210, 2023). "Histogram analysis revealed that the density of CD68+ cells gradually increased toward the tumor margin." (PMID 37792212, 2023). "Our findings suggest that immune markers are diversely expressed in GBM, with an increase in CD68+ cells indicating that macrophages/microglia increased during tumor recurrence." (PMID 37370866, 2023). "Their results showed that the higher ratio of CD163+/CD68+ macrophages in the stroma, tumour, and total tumour tissues was significantly correlated with a higher stage and grade." (PMID 37052868, 2023).
tumor (continued). "Immunohistochemical staining revealed that the tumor cells were positive for S-100, CD68, SMA, SOX-10, Calretinin, and TFE3." (PMID 37840916, 2023). "Our results support these findings, and we conclude that the quantity of epithelioid cells in a tumor correlates strongly with the number of CD68-immunopositive macrophages, and therefore with tumor malignancy." (PMID 37237550, 2023). "The tumor sections were analyzed using CD68 staining to determine the abundance and distribution of macrophages." (PMID 37553567, 2023). "Initially, we comprehensively reviewed the densities of CD3+ T cells, CD8+ T cells, FOXP3+ Tregs, and CD68+ macrophages between the paired adjacent normal tissues and the tumor tissues." (PMID 36900182, 2023). "Within all CD68/CD163 subsets as well as of the CD45+ leukocytes the MND to next tumor cells or keratinocytes was significantly lower in the HNSCC groups compared to the controls." (PMID 38322012, 2023). "In the Luminal-B group, the number of CD68 + macrophages positively correlated with tumour grade (P < 0.001)." (PMID 36622544, 2023). "Remarkably, the patient with the poorest response (75% residual tumor) also had high levels of CD68 + macrophages." (PMID 37572156, 2023). "Remarkably, we also found that the distance metrics in the MPMs revealed that mostly CD68+CD163+MRP8-14negCD86neg and M2c macrophages expressing CD68+CD163+Arg-1negMRP8-14negCD86neg were present in the tumor mass." (PMID 37958292, 2023). "We observed PGCC expressing PSMA and macrophage markers (CD68 or macrophages cocktail), strongly suggesting their tumor nature and their possible origin from cell–cell fusion." (PMID 37444476, 2023). "The plasma cells secrete IgG antibody which then binds and induces tumor cell apoptosis, possibly through a macrophage induced mechanism as evidenced by the higher infiltration of CD68+ macrophages surrounding IgG bound tumor cells." (PMID 37173966, 2023). "Tumor-infiltrating CD68 Tams were analyzed and compared with blood S100A9 MDSCs from the same patients." (PMID 36817434, 2023). "Inflammatory intratumoral macrophages (high CD68+/CD163+ ratio) and other inflammatory tumor-associated myeloid cells have been associated with improved ICI response." (PMID 37433281, 2023). "We found HLA-DR, Iba1, CD68, TREM2, P2RY12, CD64, CD16 and CD32a immunolabelled tumour-associated microglia and perivascular macrophages in the tumour cores." (PMID 37324244, 2023). "Some specimens were stained for CD3 and CD68 to control for the presence of these cellular components regarding tumor response." (PMID 38087365, 2023). "In a previous study that examined MCP-3/CCL7 in the aqueous humor of UM-containing eyes, the level of this cytokine showed correlation with the density of tumor-infiltrating CD68+ macrophages." (PMID 37509362, 2023). "In the ICECs regions at baseline, the most abundant markers of immune cells infiltrating the tumor cells were the pan-macrophage (CD68) and dendritic cell (CD11c) markers, whereas the least abundant were markers of Tregs (FOXP3) and active neutrophils (CD66b)." (PMID 37450351, 2023). "CD68-positivity of tumor cells is attributed to intracytoplasmic accumulation of phagolysosomes and does not reflect a histiocytic genesis of the tumor." (PMID 37366801, 2023). "CD68 was initially proposed to exclude macrophages, however, it has recently been reported to be expressed in dendritic cells, tumor cells, endothelial cells, and fibroblasts." (PMID 36693070, 2023). "In a microscopic evaluation, CD8+ T lymphocytes and CD68+-positive macrophages were counted in the tumor and stroma of five randomly selected fields at ×40 magnification (HPF)." (PMID 37109686, 2023). "Meanwhile, CD8+ T cells, CD4+ T cells, CD4+FoxP3+ Tregs, CD4+FoxP3− Teffs, and CD68+ TAMs were analyzed in the total, tumor, and stroma area, respectively." (PMID 37674198, 2023).
tumor (continued). "In the spatial analysis, tumour cells proximal to T-cells expressed more immune checkpoint molecules, while tumour cells closer to CD68+ macrophages and PD-L1+ macrophages were more likely to be PD-L1-." (PMID 37835491, 2023). "The stroma area covered by CD68+ macrophages ranged from 0–30% in the invading front and inner tumor areas, however, the median % was significantly lower in inner tumor areas (10% vs. 20%, p = 0.001)." (PMID 36900270, 2023). "Specifically, they showed that the presence of CD68-positive tumor-infiltrating macrophages correlates with poor prognosis in the aggressive B-cell NHL subtype." (PMID 37205092, 2023). "Multiplex immunohistochemistry (mIHC), performed in-situ on the same tissue samples as the single-cell expression, confirmed a higher infiltration of CD68+ macrophages and of CD68+ CD163+ M2-MΦ in tumor tissues compared to their matched adj-normal tissues." (PMID 36750562, 2023). "The expression of CD68—a macrophage marker—was highly expressed in the tumor stroma; however, a lesser degree of CD68-positive cells was identified in adjacent normal tissue." (PMID 36650220, 2023). "We found that tumor implantation into macrophagic NLRP3-depleted mice significantly reduced CD163-CD68+ M1 macrophages and significantly increased CD163+CD68+ M2 macrophages compared to tumor implantation into control mice." (PMID 37077909, 2023). "In pancreatic tissue, there was a significant correlation between the proportion of stromal/tumor PD-L1 + cells and the density of CD68 + /PD1 + cells." (PMID 36944944, 2023). "The tumor thrombus of OS had more CD68+ macrophages expression while CD3+ T cells were more abundant in the primary tumor lesions." (PMID 37244923, 2023). "Across all tumours, the CD68+CD163+ macrophages constituted only 5% of the CD68+ macrophages and 23% of the CD163+ cells, but demonstrated substantial inter-patient heterogeneity with cell densities ranging from 0 to 1080 cells/mm2 of tumour tissue." (PMID 36724681, 2023). "The major findings of this study are that blood vessels are mainly located in the middle of the tumor and that immune cells (especially CD68-immunopositive macrophages) are mostly found in the outer section of the tumor." (PMID 37237550, 2023). "This meta-analysis has reviewed the current literature on the prognostic potential of tissue biopsy tumour-associated macrophages; CD163+ TAMs and CD68+ TAMs as well as PD-L1 expression in OSCC." (PMID 37397243, 2023). "TMAs from HNSCC, CIS, and tumor-free samples were therefore stained sequentially with antibodies against CD68, CD163, CK, CD3, PD-1, and PD-L1." (PMID 38322012, 2023). "By contrast, we found an association between higher CD‐68 levels pre‐NET and a bigger decrease in tumour size (p = 0.03, OR: 1.016, 95% CI: 1.001–1.031)." (PMID 37553911, 2023). "We next detected IGSF6 expression, CD4+ T cell, CD8+ T cell and CD68+ macrophage cell from pathological tumor specimens with IHC." (PMID 37989761, 2023). "After low-dose radiation, iNos+CD68+ cells (M1 macrophages) in tumor tissue increase, contributing to vascular normalization, T-cell recruitment, and the inhibition of tumor progression." (PMID 36900416, 2023). "CD68+ TAMs had no prognostic significance (P = 0.158), as well as CD68+ TAMs surrounding S15− tumor cells (P = 0.088)." (PMID 37674198, 2023). "The mass channels of 129.0 m/z, 134.0 m/z Adenine, and 126.0 m/z Glycerophosphate demonstrated higher expression in tumor cells compared to CD68+ cells at a further distance from CD31+ endothelial cells." (PMID 38086839, 2023). "While high signal intensities are observed in the tumor-cell-rich solid core regions, lower TSPO signals in the tumor rim are mostly driven by CD68-positive microglia/macrophages." (PMID 37697350, 2023). "HLA-DR is associated with CD68 in primary GBM, and with CD4 in recurrent GBM, suggesting a switch between activation of M1-like macrophages and T-cell activation during tumor progression." (PMID 37370866, 2023).
tumor (continued). "To this end, we utilized immunohistochemistry with custom-made VisioPharm (Version 2018.4) analysis apps to determine the percent of total tumor area with immunoreactivity to CD68, CD3, CD4, CD8a, neutrophil elastase, and CD45r." (PMID 38136319, 2023). "In our study, we compared the expression of stromal and intratumoral CD8+ and CD68+ cells, and we analyzed their role in tumor progression." (PMID 37109686, 2023). "Compared to the inner section of the tumor, a significantly larger area was allocated to CD68-immunopositive macrophages (p = 0.003) and CD3-immunopositive T-lymphocytes (p = 0.014) in the outer section." (PMID 37237550, 2023). "Overall, these data provide further evidence that tumor cells reside in a specialized, microenvironmental, and immune-privileged niche in which they can exploit the coexisting escape pathways of the CD68/CD8 and PD-L1/PD-1 axes." (PMID 36900182, 2023). "We further confirmed the direct interaction between STAT1 and ID1 in HEK 293T cells, RAW 264.7 cells, and CD68+ TAMs in CRC patient tumor tissues by using Co-IP, proximity ligation assay (PLA) and confocal imaging." (PMID 37996458, 2023). "Other tumors, such as GBM, exhibited high levels of TREM1 expression independent from their CD68+ microglial cells, indicating that these neoplasms were intrinsically TREM1 positive." (PMID 37651197, 2023). "Our studies of MDMs suggest that some of these are M1-polarized MΦ, but based on CD68, CD80, CD163, and CD206, which are typically used for MΦ polarization, it is apparent that tumor-associated MΦ subsets occupy a broad spectrum within this classification." (PMID 38322012, 2023). "According to tumour IHC staining, the proportion of CD68-positive cells was markedly decreased upon combination treatment." (PMID 37037815, 2023). "Next, we quantified the variability of single-cell competition for tumor/T-cells and tumor/CD68+ cells for annotated metabolite channels." (PMID 38086839, 2023). "Our results coincided with the previous reports that tumours exhibiting high levels of CD68+ and CD163+ cells correlate with increased LNM, extracapsular extension, and advanced stage in HNSCC." (PMID 35963900, 2023). "Next, ccRCC specimens were immunostained for tryptase, CD68, and CD163 to estimate mast cells, total tumor-associated macrophages (TAMs), and M2-TAMs subpopulations, separately." (PMID 36902242, 2023). "Due to tumor heterogeneity, using TMA sections to evaluate CD47 tumor expression and CD68 TAM counts by IHC is a limitation of this study." (PMID 36598153, 2023). "Intra-hepatic CD68+ TAMs were associated with high HBV-DNA, high tumor differentiation, small tumor size, abnormal AFP and increased tumor number." (PMID 35347503, 2023). "In the pre‐treatment samples, we found that the TRG 1–3 group had a higher density of PD‐L1/CD68 double‐positive cells in the tumor parenchyma than the TRG 4–5 group (p = 0.048)." (PMID 36341590, 2023). "Assessment of post‐treatment changes revealed a decrease in CD20+ B cells and CD68 + TAM cell infiltration in both tumor parenchyma and stroma compared with paired pre‐treatment samples in the TRG 4–5 group, but not in the TRG 1–3." (PMID 36341590, 2023). "Tumor samples were stained for CD68+, CD163+, and CD206+, and CSF1R expression was used to determine the phenotypic expression of cells present in the tumor." (PMID 36769180, 2023). "Then Siglec-15 expression in the tumor and macrophage compartment were analyzed separately by mfIHC, in which CK+ cells were defined as the tumor compartment (TC), CD68+ cells as the macrophage compartment (MC), and CK− cells as the stroma compartment (SC)." (PMID 37674198, 2023). "By TCGA and TISIDB analysis, the downregulation of Act1 expression in tumor tissues of CRC patients negatively correlated with accumulated CD68+ macrophages in the tumor." (PMID 36978108, 2023).
tumor (continued). "CD68 is an immunohistochemical marker of macrophage cells, which have various functions in immunity, inflammation, and tumor biology." (PMID 37048097, 2023). "B7-H3 and STING are the most expressed antigens in primary tumors (both in the center and the peripheral zones), while CD68 and CD11c were found only at the periphery of the tumor." (PMID 37370866, 2023). "Among these cancer types, tumor-associated macrophage (TAM) markers such as CCL2, CD68, CD80, and IL10 had strong or moderate correlations with NNMT expression." (PMID 36817086, 2023). "We identified a higher percentage of IDO1+ cells among CD68+ and 163+ TAMs in tumour tissue than in healthy adjacent tissue (t test, p < 0.01)." (PMID 35963900, 2023). "In this study, we found that the low-grade group showed significantly more CD68+ macrophages in both the tumor and total region compared with the high-grade group." (PMID 38023213, 2023). "Immunohistochemical (IHC) staining results indicated that CD68+ macrophages were evenly distributed in normal and tumor-adjacent tissue, while in tumor tissue, they were mainly enriched around the stroma." (PMID 37308559, 2023). "Some studies have also found that tumor-associated macrophage-related molecular markers and secreted cytokines, such as CD163, CD206/CD68, and IL-10, were related to the prognosis of HGSOC." (PMID 37124547, 2023). "It was found that there was an increase in area of FR-α and CD68 fluorescence signal inside the tumor area versus adjacent healthy brain tissue." (PMID 37275898, 2023). "Immunohistochemistry using anti-CD34 antibody was used to identify micro-vessels, and anti-CD-68 antibody was used to identify TAMs in tumour tissues." (PMID 37052868, 2023). "The localization of CD68+ MΦ in the tumor microenvironment, among other factors, appears to play a major role for clinical outcome." (PMID 38322012, 2023). "Results show that C3AR1 has the strongest correlation with M2 macrophages (CD163, MRC1, CD209), tumor-associated macrophages (CCL2, CD86, CD68) and monocyte immune markers, including (CD14, CD33, ITGAX)." (PMID 37005667, 2023). "We found that stromal features, including stromal maturity and volume, were closely related to CD68+ macrophage infiltration in the whole tumor area." (PMID 37405518, 2023). "An additional circulating innate subpopulation, possibly of monocytic origin, has been recently identified consisting of cytotoxic CD3-CD4+CD68+GrB+ cells, which are also detectable in cHL tumor sections." (PMID 36910620, 2023). "The tumor periphery demonstrated significantly higher densities of total CD68+ macrophages (median of 68.28 cells/mm2) compared to the tumor center (12.96 cells/mm2)." (PMID 37637998, 2023). "Together, these observations suggest that the immune system is successfully mounting an attack against tumor cells (cytotoxic T cells, M1 macrophages), despite tumor cell PD-L1 expression and presence of M2 macrophages (CD68 and CD163)." (PMID 35379804, 2022). "While the link between macrophage marker CD68 and outcome has been ambiguous, CD68+ cell counts located at the invasive front of the tumour has been noted to be a predictor of reduced survival." (PMID 35664673, 2022). "Previous studies have reported the expression of CD68 by other cells, including fibroblasts, endothelial cells, and tumor cells." (PMID 35158887, 2022). "More interestingly, immunofluorescence double staining was conducted, and the tumor tissue-accumulated macrophages were CD68+CD163+ macrophages (M2-polarized macrophages), indicating a greater importance of the M2 subtype in OSCC progression." (PMID 35090495, 2022). "In ccRCC samples with CCL5 upregulation, the proportion of CCL5+ TAMs and PD-L1+ CD68+ TAMs were prominently increased, showing a typical suppressive tumor immune microenvironment (TIME)." (PMID 35982911, 2022).